GALNT3 (polypeptide N-acetylgalactosaminyltransferase 3)
Description:
Catalyzes the initial reaction in O-linked oligosaccharide biosynthesis, the transfer of an N-acetyl-D-galactosamine residue to a serine or threonine residue on the protein receptor. Has activity toward HIV envelope glycoprotein gp120, EA2, MUC2, MUC1A and MUC5AC. Probably glycosylates fibronectin in vivo. Glycosylates FGF23.
Synonyms: GalNAc-T3; HHS; HFTC; HFTC1
Tractability: Antibody: UniProt predicts a signal peptide or a membrane-spanning region. PROTAC: a small molecule that binds it is known.
Target class: Enzyme; Transferase
Gene: Protein-coding gene on chromosome 2 (165,747,588 to 165,846,201, reverse strand). Ensembl gene ENSG00000115339.
Subcellular location: Golgi apparatus, Golgi stack membrane
Subcellular location (Human Protein Atlas): Golgi apparatus
Pathways (Reactome):
Disease: Defective GALNT3 causes HFTC
Metabolism of proteins: O-linked glycosylation of mucins
Signal Transduction: FGFR3c ligand binding and activation
Gene Ontology:
Molecular function: calcium ion binding; manganese ion binding; polypeptide N-acetylgalactosaminyltransferase activity
Biological process: protein O-linked glycosylation; protein O-linked glycosylation via N-acetyl-galactosamine; fibroblast growth factor receptor signaling pathway
Cellular component: extracellular exosome; Golgi apparatus; perinuclear region of cytoplasm; Golgi membrane; membrane; cytoplasm; Golgi cisterna membrane
Genetic constraint (gnomAD): Loss-of-function variants: 37 observed, 60.51 expected, observed/expected ratio (o/e) 0.61, 90% interval 0.47 to 0.8. The upper end of that interval is the gene's LOEUF score, 0.8, which puts it in group 3 of 6, group 1 being the genes least tolerant of losing a copy. Missense variants: 669 observed, 738.04 expected, observed/expected ratio (o/e) 0.91, 90% interval 0.85 to 0.97. Synonymous variants: 251 observed, 246.85 expected, observed/expected ratio (o/e) 1.02, 90% interval 0.92 to 1.13.
Gene-disease validity (ClinGen):
ClinGen rates the evidence that GALNT3 causes each of these diseases.
tumoral calcinosis, hyperphosphatemic, familial, 1 (autosomal recessive): Definitive.
Homologues: Orthologues: macaque GALNT3 (99% identical), chimpanzee GALNT3 (99% identical), pig GALNT3 (97% identical), dog GALNT3 (95% identical), rabbit GALNT3 (95% identical), guinea pig GALNT3 (92% identical), mouse Galnt3 (92% identical), rat Galnt3 (92% identical), tropical clawed frog galnt3 (73% identical), zebrafish GALNT3 (70% identical), Caenorhabditis elegans gly-5 (38% identical), Drosophila melanogaster Pgant9 (37% identical), and 2 more. Paralogues in human: GALNT6 (64% identical), GALNT4 (40% identical), GALNT12 (37% identical), GALNT1 (37% identical), GALNT13 (37% identical), GALNT5 (34% identical), GALNT16 (34% identical), GALNT11 (34% identical), GALNT14 (33% identical), GALNT2 (33% identical), GALNT15 (32% identical), GALNTL6 (32% identical), and 7 more.
Diseases named in the same sentence as GALNT3 in open-access papers:
GALNT3 is named in the same sentence as 55 diseases in open-access papers, as found by Europe PMC text mining. Sharing a sentence is not in itself a finding about the gene and the disease. The quoted sentences say what the papers report.
hyperphosphatemia (17 papers, 2010 to 2025). Abnormally high level of phosphate in the blood. "The first described human CDG caused by deficiency in a GALNT gene (GALNT3) also caused a distinct phenotype associated with hyperphosphatemia and ectopic calcifications (Familial Tumoral Calcinosis – FTC, GALNT3-CDG)." (PMID 40449597, 2025). "These GALNT3 mutations lead to increased bone mass, hyperphosphataemia and extraskeletal calcification mediated by reduced FGF23 glycosylation." (PMID 41278200, 2025). "In contrast, Tcal/Tcal mice, which feature a missense mutation in the Galnt3 gene, feature hyperphosphatemia and extensive ectopic calcification." (PMID 32210002, 2020). "Galnt3: Patients with mutations in Galnt3 suffer from hyperphosphatemia and extensive calcium depositions." (PMID 32210002, 2020). "Another HFTC mouse created by ENU mutagenesis harbors a Trp589Arg mutation in Galnt3, and also has hyperphosphatemia with decreased intact FGF23 levels, elevated 1,25D, and subtle periarticular calcifications." (PMID 32457699, 2020). "In the mouse model developed by Ichikawa and colleagues, the ablation of GALNT3 in exons 2 and 3 led to decreased circulating intact Fgf23 levels with hyperphosphatemia, despite that high levels of Fgf23 were found in bone." (PMID 40149415, 2025). "In another TC mouse model, a Trp589Arg GALNT3 mutation was generated by N-ethyl-N-nitrosourea (ENU) mutagenesis, resulting in hyperphosphatemia associated with decreased intact FGF23 levels, increased 1α,25(OH)2D3 levels, and periarticular calcified masses." (PMID 40149415, 2025). "Although pathogenesis has not been fully understood, mutations in genes such as GalNAc transferase 3 (GALNT3), FGF23, and KLOTHO cause hyperphosphatemia, causing calcific deposits to fill neo-bursae created by dysfunctional histiocytes." (PMID 40218160, 2025). "Galnt3−/− mice exhibited hyperphosphatemia and hypercalcemia, and the intact Fgf23 was about 40% that of wild-type mice." (PMID 38396954, 2024). "Although both Galnt3−/− mice and Fgf23−/− mice showed hyperphosphatemia and hypercalcemia, the bone phenotypes in Galnt3−/− mice were quite different from those in Fgf23−/− mice." (PMID 38396954, 2024). "Bi‐allelic loss‐of‐function GALNT3 mutations alter FGF23 metabolism, resulting in hyperphosphatemia and causing familial tumoral calcinosis (FTC)." (PMID 36824040, 2023). "Results from mice models are contradicting: Galnt3−/− mice have hyperphosphatemia and increased FGF23 expression, although secretion of intact FGF23 is impaired, but show no sign of abnormal calcification." (PMID 32210002, 2020). "Our female subject is the first reported case of band keratopathy in GALNT3 associated HFTC and HHS, and this outcome is probably the result of 50 years of untreated hyperphosphatemia." (PMID 25249269, 2014). "Hyperphosphatemic familial tumoral calcinosis (HFTC) is a rare autosomal recessive disorder characterized by ectopic calcifications in periarticular soft tissues due to mutations in genes such as GALNT3, FGF23, or KL, leading to FGF23 deficiency or resistance and subsequent hyperphosphatemia." (PMID 40524990, 2025). "Thus, Galnt3−/− mice clearly show the effects of hyperphosphatemia and hypercalcemia on bone development and maintenance." (PMID 38396954, 2024). "In Galnt3−/− mice, breeding with FGF23 transgenic mice can increase the amount of intact FGF23 and reduce hyperphosphatemia." (PMID 32210002, 2020).
familial tumoral calcinosis (12 papers, 2014 to 2025). Tumoral calcinosis is a phosphocalcic metabolism anomaly, particularly among younger age groups and characterized by the presence of calcified masses in the juxta-articular regions (hip, elbow, ankle and scapula) without joint involvement. "Biallelic LoF GALNT3 variants are known to be associated with the extremely rare autosomal recessive conditions of hyperphosphatemic familial tumoral calcinosis (FTC) and hyperostosis‐hyperphosphatemia syndrome (HHS) (OMIM: 211900)." (PMID 36824040, 2023). "Mutations in FGF23, KL, and GALNT3 have been identified as the cause for the development of hyperphosphatemic familial tumoral calcinosis (HFTC)." (PMID 34270404, 2021). "Hyperphosphatemic familial tumoral calcinosis (FTC) is a rare genetic disorder resulting from the mutations in FGF23, GALNT3, or KL genes." (PMID 34199304, 2021). "Hyperphosphatemic familial tumoral calcinosis (HFTC) is a rare autosomal recessive disorder caused by mutations in FGF23, GALNT3, KLOTHO, or FGF23 autoantibodies." (PMID 33977199, 2021). "Inactivating autosomal recessive mutations in fibroblast growth factor 23 (FGF23), klotho (KL) and polypeptide N-acetylgalactosaminotransferase 3 (GALNT3) genes lead to a rare disorder, hyperphosphatemic familial tumoral calcinosis (HFTC)." (PMID 30015621, 2019). "Hyperphosphatemic Familial Tumoral Calcinosis (HFTC) and Hyperphosphatemic Hyperostosis Syndrome (HHS) are associated with autosomal recessive mutations in three different genes, FGF23, GALNT3 and KL, leading to reduced levels of fibroblast growth factor 23 (FGF23) and subsequent clinical effects." (PMID 25249269, 2014).
ovarian carcinoma (11 papers, 2014 to 2025). A malignant neoplasm originating from the surface ovarian epithelium. "Polypeptide N-acetylgalactosaminyltransferase 3 (Galnt3) was upregulated in 4T1 and overexpression of this gene is associated with shorter progression-free survival in advanced ovarian cancer." (PMID 32793490, 2020). "GALNT3 is notably overexpressed in high-grade serous epithelial ovarian cancer, influencing metabolic pathways and post-translational modifications within ovarian cancer cells." (PMID 41171827, 2025). "Conversely, high expression of GALNT3 is detected in oral squamous cell carcinomas and ovarian cancer." (PMID 35184747, 2022). "GALNT3 is overexpressed in some cancers including PC, and is known for its tumor-promoting role in pancreatic and ovarian cancers." (PMID 30466404, 2018). "The data presented here was obtained with the application of a bioorthogonal chemical reporter strategy analyzing differential glycoprotein expression following the knock-down (KD) of the GALNT3 gene in the epithelial ovarian cancer (EOC) cell line A2780s." (PMID 27331112, 2016). "GALNT3 protein is known to be overexpressed in high-grade serous epithelial ovarian cancer tumours and has a role in modulating post-translational modifications and metabolism pathways in ovarian cancer cells." (PMID 34413360, 2021). "Moreover, the GALNT3 expression significantly correlated with shorter progression-free survival (PFS) intervals in epithelial ovarian cancer (EOC) patients with advanced disease." (PMID 24504219, 2014). "The downregulation of the MUC1 protein, observed in our study upon knocking down both the GALNT3 and GALNT6 genes, emphasizes its possible role in enhancing the malignant phenotype of ovarian cancer." (PMID 31071912, 2019). "One study showed that GALNT3 is up-regulated in high-grade serous EOC and is correlated with shorter progression-free survival in advanced stage ovarian cancer." (PMID 28388560, 2017). "Moreover, knockdown of the glycosyltransferase responsible for synthesis of MUC1 and MUC13, N-acetylgalactosaminyltransferase 3 (GALNT3) and GALNT14, respectively, reduces migration of ovarian cancer cells." (PMID 32785160, 2020).
pancreatic cancer (10 papers, 2015 to 2023). "GALNT3 is an enzyme for O-glycosylation, and down-regulation of GALNT3 has been reported to be associated with poor prognosis of lung adenocarcinoma, colorectal cancer, and pancreatic cancer." (PMID 35184747, 2022). "Loss of GALNT3 in pancreatic cancer was related to aberrant O-glycosylation of the ErbB family." (PMID 36058918, 2022). "Since KLF5 and TCF7L2 have been shown to be upregulated in pancreatic cancer stem cells, it would be interesting to validate if GALNT3 and B3GNT3 are driven by any of these TFs." (PMID 34367349, 2021). "O-Linked glycosylation via GALNT3 and B3GNT3 has been shown to regulate differentiation of pancreatic cancer stem cells." (PMID 34367349, 2021). "Similar to PaTu-S, a high GALNT3 expression was observed in human pancreatic cancer tissues." (PMID 32582529, 2020). "Reports showed that dysregulation of GALNT3 and GALNT6 promote the metastatic phenotypes pancreatic cancer." (PMID 36925932, 2023). "GALNT3 was predicted as an independent prognostic factor in renal cell carcinomas, and GALNT6 was found to function in pancreatic cancer." (PMID 29970122, 2018).
colorectal cancer (9 papers, 2014 to 2022). A primary or metastatic malignant neoplasm that affects the colon or rectum. "It is also involved in “Defective GALNT12 causes colorectal cancer 1 (CRCS1)” and “Defective GALNT3 causes familial hyperphosphatemic tumoral calcinosis (HFTC)” pathways based on the Reactome Pathways database." (PMID 35439935, 2022). "The abundance of GALNT1 and GALNT2 has been found to be significantly higher in colorectal cancer than that in normal epithelium, and high GALNT3 protein expression has been reported to be an indicator of tumor differentiation and a prognostic factor in colorectal cancer." (PMID 35692787, 2022). "Both GALNT3 and GALNT6 displayed oncogenic functions in different cancer types; GALNT3 has often been suggested as a possible therapeutic target in pancreatic, gastric, and colorectal cancers." (PMID 31071912, 2019). "However, GALNT3 expression is also shown to be a negative indicator for disease prognosis in non-small cell lung cancer and colorectal carcinoma, including colon carcinoma cells selected for hepatic metastasis." (PMID 24504219, 2014).
lung carcinoma (6 papers, 2022 to 2025). "GALNT3 restricts the recruitment of polymorphonuclear myeloid-derived suppressor cells (PMN-MDSCs) by inhibiting the self-renewal of lung cancer cells, which leads to the downregulation of CXCL1." (PMID 40407951, 2025). "Research indicates that the expression of polypeptide N-acetyl-galactosaminyltransferase 3 (GALNT3) is diminished in lung cancer tissues compared to normal lung tissues." (PMID 40407951, 2025). "GALNT-3 has recently been implicatedin lung cancer development and regulation of the tumor microenvironmentusing in vitro and in vivo models." (PMID 39772544, 2025). "GALNT3 was developed to prevent lung cancer by preventing self-renewal and the development of a favorable tumor microenvironment." (PMID 37427142, 2023). "GALNT3 is reported to play a tumor-suppressive role in familial tumoral calcinosis 27 and lung cancer 28 and shows a median dependency score >0 in NB cell lines; however, there is no available study regarding GALNT3 in NB." (PMID 35517412, 2022). "IHC results also confirmed that GALNT3, CYCS, EIF5A, and ITGB4 were highly expressed in lung cancer tissues than normal lung tissues." (PMID 35651789, 2022).
breast carcinoma (5 papers, 2014 to 2023). "Further studies are necessary to verify possible GALNT3/T6 redundancies in other cancer types, and especially in breast cancer, where GALNT6 has displayed quite similar functions in mediating aberrant O-glycosylation, as found by us for GALNT3 in EOC." (PMID 31071912, 2019). "Reduced expression of GALNT3 was previously reported in mesenchymal trophoblast stem cells and breast cancer cells, suggesting that GALNT3 may be important in promoting an epithelial phenotype." (PMID 37046045, 2023). "Moreover, GALNT6 exhibits analogous oncogenic functions in breast cancer (modulating aberrant O-glycosylation and MUC1 stabilization), similar to observations found by us for GALNT3 in EOC dissemination." (PMID 31071912, 2019). "Thus far, there are no reported connections between GALNT3 and CIT expression and breast cancer." (PMID 37391533, 2023).
hyperostosis (5 papers, 2016 to 2024). Excessive thickening of bone. "Two other diseases in group 24 (other sclerosing bone disorders), hyperostosis–hyperphosphatemia syndrome, caused by mutations in GALNT3 gene, and Lenz–Majewski hyperostotic dysplasia, a result of PTDSS1 mutations, have been modeled in zebrafish." (PMID 34490030, 2021). "Mutations in the GALNT3 gene were shown to account for the hyperphosphatemic state in both HFTC and hyperostosis-hyperphosphatemia syndrome (HHS), the latter characterized by bone involvement." (PMID 34270404, 2021). "In addition, our patients did not present bone lesions, such as hyperostosis; therefore, hyperostosis-hyperphosphatemia syndrome, which also results from mutations in the GALNT3 gene, could be excluded." (PMID 27867679, 2016).
calcinosis (4 papers, 2012 to 2025). Deposition of calcium in the tissues. "Our case is about a patient with GALNT3 mutation and several localizations of refractory calcinosis." (PMID 31372591, 2019). "The differences in the sizes of the calcinosis lesions between human FTC and the Tcal/Tcal and Galnt3-deficient mouse models, may in part be attributed to the observed variability of FTC lesions in man." (PMID 22912827, 2012). "Studies investigating the responses to injury and the underlying inflammatory and immune mechanisms in the Tcal/Tcal mice, which have calcinosis lesions, and in the Galnt3-deficient mice, which do not have calcinosis lesions, may help to elucidate the basis of these differences." (PMID 22912827, 2012). "Similarly, patient 7, who had normal pulp morphology, did not have a GALNT3 or FGF23 mutation, and did not have findings consistent with a KLOTHO mutation, had classic calcinosis findings, a markedly elevated cFGF23, and a blood phosphate that was at the upper limit of the normal range." (PMID 33977199, 2021).
cervical cancer (4 papers, 2022 to 2025). A primary or metastatic malignant neoplasm involving the cervix. "This study revealed MPP5, SNX7, LSM12, and GALNT3 as genes linked to the prognosis of cervical cancer patients receiving concurrent radiotherapy, through the analysis of the GEO database." (PMID 41171827, 2025). "Another study showed that PSMA3-AS1 can activate the PI3K/AKT pathway to promote cervical cancer proliferation and metastasis through the pathway of miR-378a-3p regulating GALNT3." (PMID 37088992, 2023). "Here in cervical cancer, we observed up-regulated GALNT3 compared with normal cervical tissues, particularly in high-risk group." (PMID 35184747, 2022). "The prognostic risk model constructed in this study, based on the four genes MPP5, SNX7, LSM12, and GALNT3, demonstrated promising predictive performance for radiotherapy outcomes in cervical cancer patients, particularly in the medium- to long-term follow-up, with an AUC of 0.75 at 3 years." (PMID 41171827, 2025).
non-small cell lung carcinoma (4 papers, 2013 to 2016). A group of at least three distinct histological types of lung cancer, including non-small cell squamous cell carcinoma, adenocarcinoma, and large cell carcinoma. "The low expression of GALNT3 in non-small cell lung carcinoma (NSCLC) was shown to be an unfavorable prognostic factor for stage-I NSCLC and stage-I non-squamous cell carcinomas." (PMID 27322213, 2016). "For instance, GALNT3 was proposed as a marker of non-small cell lung cancer prognosis, whereas GALNT6 and GALNT14 itself were proposed as potential tissue biomarkers, since their high expression in breast and gastric carcinomas." (PMID 26309160, 2015).
renal cell carcinoma (4 papers, 2015 to 2018). "High level of GALNT3 was closely associated with poor disease-specific survival in renal cell carcinoma with a significant hazard ratio (HR = 3.43)." (PMID 28122358, 2017). "For example, GALNT3 expression level has been identified to be significantly associated with tumor behavior or prognosis in pancreas adenocarcinoma, renal cell carcinoma and gastric cancer; GALNT6 is an independent indicator in mammary cancer." (PMID 28122358, 2017). "GALNT3 is frequently up-regulated in renal cell carcinoma (RCC) and independently predicts high-grade tumor and poor survival; similarly GALNT3 is also up-regulated in high-grade serous epithelial ovarian cancer (EOC) and is correlated with shorter progression-free survival in advanced stage EOC." (PMID 25730904, 2015).